IL12RB1 (interleukin 12 receptor subunit beta 1)
Description:
Functions as an interleukin receptor which binds interleukin-12 with low affinity and is involved in IL12 transduction. Associated with IL12RB2 it forms a functional, high affinity receptor for IL12. Also associates with IL23R to form the interleukin-23 receptor which functions in IL23 signal transduction probably through activation of the Jak-Stat signaling cascade.
Synonyms: CD212; IL12RB; IL-12R-BETA1; IMD30
Tractability: Antibody: its Gene Ontology location is reachable by antibodies, with high confidence; UniProt predicts a signal peptide or a membrane-spanning region; the Human Protein Atlas places it where antibodies can reach.
Target class: Membrane receptor
Gene: Protein-coding gene on chromosome 19 (18,058,995 to 18,098,944, reverse strand). Ensembl gene ENSG00000096996.
Subcellular location: Membrane
Subcellular location (Human Protein Atlas): Plasma membrane
Pathways (Reactome):
Immune System: Interleukin-12 signaling; Interleukin-23 signaling
Gene Ontology:
Molecular function: coreceptor activity; interleukin-12 receptor activity; interleukin-12 receptor binding; interleukin-23 binding; interleukin-23 receptor activity; cytokine binding; cytokine receptor activity
Biological process: cellular response to type II interferon; interleukin-12-mediated signaling pathway; interleukin-23-mediated signaling pathway; positive regulation of activated T cell proliferation; positive regulation of defense response to virus by host; positive regulation of T-helper 1 type immune response; positive regulation of type II interferon production; cytokine-mediated signaling pathway; positive regulation of cell population proliferation; positive regulation of memory T cell differentiation; positive regulation of T cell mediated cytotoxicity; positive regulation of T-helper 17 cell lineage commitment; positive regulation of T-helper 17 type immune response; signal transduction
Cellular component: interleukin-12 receptor complex; interleukin-23 receptor complex; external side of plasma membrane; plasma membrane; receptor complex; membrane
Genetic constraint (gnomAD): Loss-of-function variants: 35 observed, 53.85 expected, observed/expected ratio (o/e) 0.65, 90% interval 0.5 to 0.86. The upper end of that interval is the gene's LOEUF score, 0.86, which puts it in group 3 of 6, group 1 being the genes least tolerant of losing a copy. Missense variants: 543 observed, 580.66 expected, observed/expected ratio (o/e) 0.94, 90% interval 0.87 to 1. Synonymous variants: 243 observed, 244.92 expected, observed/expected ratio (o/e) 0.99, 90% interval 0.89 to 1.1.
Homologues: Orthologues: chimpanzee IL12RB1 (99% identical), macaque IL12RB1 (94% identical), dog IL12RB1 (70% identical), pig IL12RB1 (69% identical), mouse Il12rb1 (53% identical), rat Il12rb1 (52% identical), tropical clawed frog il12rb1 (22% identical), zebrafish lifra (12% identical), zebrafish lifrb (10% identical), zebrafish ghra (8% identical), zebrafish ghrb (8% identical), zebrafish il11ra (7% identical), and 1 more. Paralogues in human: IL6ST (16% identical), IL31RA (16% identical), CSF3R (14% identical), IL12RB2 (13% identical), LIFR (13% identical), LEPR (12% identical), OSMR (12% identical), IL27RA (12% identical), PRLR (10% identical), IL23R (10% identical), IL5RA (9% identical), GHR (8% identical), and 11 more.
Diseases named in the same sentence as IL12RB1 in open-access papers:
IL12RB1 is named in the same sentence as 120 diseases in open-access papers, as found by Europe PMC text mining. Sharing a sentence is not in itself a finding about the gene and the disease. The quoted sentences say what the papers report.
tuberculosis (12 papers, 2008 to 2025). A chronic, recurrent infection caused by the bacterium Mycobacterium tuberculosis. "Certain single-nucleotide polymorphisms (SNPs) in IL12RB1, such as the R214-T365-R378 allele, are associated with increased tuberculosis risk, highlighting how receptor variants alter IL-12 signaling." (PMID 40519922, 2025). "IL12Rβ1 deficiency has been associated with childhood-onset and recurrence of salmonellosis, tuberculosis, and candidiasis indicating its role in the prevention of bacterial and fungal infection." (PMID 37287978, 2023). "In this study, we investigated the mechanism of tuberculosis suppression using the IL12RB1-deficient mouse model." (PMID 35891311, 2022). "We aimed to estimate the fraction of children developing severe tuberculosis due to IL-12Rβ1 deficiency in areas endemic for tuberculosis and where parental consanguinity is common." (PMID 21533230, 2011). "In addition, IL-12Rβ1 deficiency was the first primary immunodeficiency to be associated with pediatric tuberculosis in children with normal resistance to BCG and environmental mycobacteria (EM)." (PMID 29256176, 2018). "IL-12Rβ1 deficiency has been diagnosed in several children and teenagers with tuberculosis (TB)." (PMID 29256176, 2018). "In the last decade, autosomal recessive interleukin-12 receptor β1 (IL-12Rβ1) deficiency, the most common cause of Mendelian susceptibility to mycobacterial disease (MSMD), has been diagnosed in a few children and adults with severe tuberculosis in Iran." (PMID 29256176, 2018). "Low IL-12Rβ1 expressing PBMCs has been detected in tuberculosis patients." (PMID 22509293, 2012). "However, both IL-12Rβ1 & β2 mRNA in bronchoalveolar lavage have been detected in tuberculosis patients." (PMID 22509293, 2012). "Despite the small sample studied, our findings suggest that IL-12Rβ1 deficiency is not a very rare cause of pediatric tuberculosis in these countries, where it should be considered in selected children with severe disease." (PMID 21533230, 2011).
chronic mucocutaneous candidiasis (8 papers, 2018 to 2024). "About 25% of patients with IL-12Rβ1 or IL-12p40 deficiency also suffer from chronic mucocutaneous candidiasis (CMC)." (PMID 36763636, 2023). "Patient P-Jap was the only TYK2-deficient patient reported to suffer from chronic mucocutaneous candidiasis, which was attributed to impaired IL-12 and IL-23 responses and defective Th17 immunity, as seen in patients with IL-12Rβ1 deficiency." (PMID 36094518, 2022). "However, the susceptibility of certain individuals with deficiencies in IL-12B, IL-12Rβ1, or IL-23R to chronic mucocutaneous candidiasis (CMC) indicates the crucial role of human IL-23 in defending against mucocutaneous Candida spp." (PMID 38535546, 2024). "Notably, patients with LOF mutations in IL12RB1 or RORC both are susceptible to chronic mucocutaneous candidiasis (CMC) resulting from infection with the common opportunistic fungal pathogen Candida albicans." (PMID 35896601, 2022). "Patients with autosomal recessive (AR) IL-12p40 or IL-12Rβ1 deficiency display Mendelian susceptibility to mycobacterial disease (MSMD) due to impaired IFN-γ production and, less commonly, chronic mucocutaneous candidiasis (CMC) due to impaired IL-17A/F production." (PMID 36763636, 2023). "Susceptibility to predominantly viral infections was observed in TET2, TPP2 and TNFAIP3 patients while chronic mucocutaneous candidiasis (CMC) and mendelian susceptibility to mycobacterial disease (MSMD) were characteristic of STAT1 GOF and IL12RB1 patients, respectively." (PMID 34447369, 2021).
COVID-19 (8 papers, 2021 to 2025). A disease caused by infection with severe acute respiratory syndrome coronavirus 2. "Notably, whereas IL12RB1, NRP1 and NRP2 were only moderately increased as a function of viral load, CNTN1 expression was significantly correlated with viral load in these COVID-19 patients, an association that was more prominent in older patients." (PMID 35931765, 2022). "The higher disease severity and mortality of COVID-19 observed in the African American population might be explained—at least in part—by the higher expression of IL-1β, IL-18 receptor, IL-12Rβ1, and some toll-like receptors." (PMID 33996683, 2021). "However, IL12RB1 and IL12RB2 transcript levels as well as those encoding for the cytokines, IL15 and IL12 (IL15 and IL12A, respectively) decreased in life-threatening COVID-19 and MIS-C." (PMID 41285788, 2025).
candidiasis (7 papers, 2011 to 2023). Infection with the organism Candida. "The P1, who had a mutation in the IL12RB1 gene, manifested an oral Candida infection as the only infection as a consequence of her PID." (PMID 30627128, 2018). "The role of IL-12p80, which is capable of binding both the IL-12R and IL-23R via the IL-12Rb1 subunit, also generates a phenotype that remains underexplored in mouse models of candidiasis, or in human clinical disease, because of this structural overlap." (PMID 21052539, 2011).
fungal infections (6 papers, 2017 to 2024). "The susceptibility to endemic mycoses in CD40L, NEMO, IL12Rβ1 and IFN-γR1 deficiencies highlights the critical role of IL-12/IFN-γ crosstalk in macrophage activation and killing of these dimorphic fungi." (PMID 31572394, 2019). "In fact, IL12Rβ1, NEMO, CD40L, and IFNγR1 deficiencies also result in impaired Th17 generation from naïve T-cells which likely contribute to susceptibility to fungal infection." (PMID 31572394, 2019). "Endemic fungal infections have been reported in AR IL12Rβ1, AR IFN-γR1, and AD GOF STAT1 defects." (PMID 28702025, 2017). "While the relative distributions of ILCs in tissues from both RORC and IL12RB1 patients is not known, the observed defects in their generation of Group 3 ILCs from ILCP may contribute to their susceptibility to fungal infections." (PMID 35896601, 2022).
Immunodeficiency (6 papers, 2018 to 2026). Failure of the immune system to protect the body adequately from infection, due to the absence or insufficiency of some component process or substance. "Here, we present a case of a disseminated infection with Mycobacterium genavense owing to an interleukin 12 receptor subunit beta 1 (IL-12Rβ1) associated immunodeficiency in a previously healthy female who was initially misdiagnosed with sarcoidosis." (PMID 36192705, 2022). "IL-12Rβ1 deficiency is an autosomal recessive, hereditary immunodeficiency that is part of a complex of genetic disorders termed Mendelian susceptibility to mycobacterial diseases (MSMD)." (PMID 36192705, 2022). "We reported two cases of IL12RB1 mutation in children infected with T. marneffei, extending the immunodeficiency spectrum of T. marneffei infection." (PMID 36159645, 2022). "Patients with immunodeficiency caused by mutations in the IL-12Rβ1 gene often become symptomatic with infections in childhood." (PMID 36192705, 2022). "These identified a homozygous pathogenic variant p(Cys198Arg) (c.592T > C) in the IL12RB1 gene (NM_005535, rs121434495), previously reported in attenuated IL-12Rβ1-associated immunodeficiency." (PMID 36192705, 2022). "Here, we present a case of a disseminated infection with the opportunistic pathogen Mycobacterium genavense owing to an interleukin 12 receptor subunit beta 1 (IL-12Rβ1) associated immunodeficiency in a previously healthy female who was initially misdiagnosed with sarcoidosis." (PMID 36192705, 2022). "Patients with IL-12Rβ1-associated immunodeficiency may be asymptomatic until adulthood, and disseminated M. genavense infection on the grounds of an IL-12Rβ1-associated immunodeficiency may represent a rare differential diagnosis of sarcoidosis." (PMID 36192705, 2022). "Mutations in 6 genes (IL12RB1, CYBB, IFNGR1, IL2RG, STAT1, and RAG1) account for 66% of BCG-associated immunodeficiency mutations." (PMID 41748971, 2026).
Salmonella Infections (6 papers, 2006 to 2025). Infections with bacteria of the genus SALMONELLA. "Autosomal recessive IL-12B or IL-12Rβ1 gene mutations, causing IL-12Rβ1 or IL-12p40 deficiency, affecting both IL-12 and IL-23 signaling pathways, leads to mycobacterial infections in 83% of patients, to Salmonella infections in 43% and CMC in 23% of patients." (PMID 29371502, 2018). "In conclusion, cutaneous vasculitis in MSMD patients could be pathognomic of an underlying IL12B or IL12Rβ1 deficiency, particularly in those complicated with Salmonella infections." (PMID 34389021, 2021). "Sixteen patients (88.9%) had IL12RB1 defects and concurrent Salmonella infection was reported in 15 (88.2%) patients." (PMID 34389021, 2021). "Most of the reported MSMD patients with vasculitis (n = 16, 88.9%) had IL12RB1 defects, and concurrent Salmonella infection was reported in 15 (88.2%) patients as IL-12 pathway is involved during Salmonella infection." (PMID 34389021, 2021). "For example, IL12RB1 loss-of-function mutations abolish IL-12 receptor β1 expression, resulting in absent IFN-γ production after IL-12 stimulation, which explains the high burden of disseminated mycobacterial and salmonella infections." (PMID 41209815, 2025). "Only one patient, PID04, presented with recurrent Salmonella infection, which is a common MSMD presentation associated with mutations in IL12RB1 and IL12B, however, no plausible disease-causing variants in either of these genes were identified in this patient through WES." (PMID 34517836, 2021).
breast carcinoma (5 papers, 2019 to 2023). "The IL-12RB1 polymorphisms have been explored in other cancers including cervical cancer; breast cancer; esophageal cancer; and gastric cancer." (PMID 35646062, 2022). "In fact, several studies have been carried out to explore the association between IL-12RB1 polymorphisms and certain diseases such as cervical cancer, breast cancer, and tuberculosis." (PMID 35646062, 2022). "It is therefore possible that the association between genetic variants in IL12RB1 and breast cancer be confounded by education level as a result of an increased prevalence of chronic diseases in the control group, due to recruitment strategies." (PMID 32973967, 2020). "The results show that most of the cytokines or cytokine receptors (except IL12 and IL12RB1) were related to breast cancer or metastasis." (PMID 31557971, 2019). "Both STAT3 and STAT4 were responsible for the transcription of IL12RB1 and IL12RB2 in breast cancer cell." (PMID 38107057, 2023). "Bioinformatic analysis in breast cancer has shown that high expression of IL-12/STAT4 axis molecules, such as the IL-12 receptor genes (IL-12RB1 and IL-12RB2), STAT4, IFNγ, and TBX21, significantly increases the survival rates of patients with breast cancer, especially the more aggressive subtypes." (PMID 33076315, 2020).
inflammatory bowel disease (5 papers, 2014 to 2024). A spectrum of small and large bowel inflammatory diseases of unknown etiology. "Other polymorphisms in IL12RB1 have been associated with M. tuberculosis, inflammatory bowel disease and psoriasis." (PMID 25255143, 2014). "In 5-Tm, GOs including Th17 differentiation pathway, inflammatory bowel disease, and allograft rejection, represented by IL12RB1, IRF4, LAT, and IL22, were observed in PE." (PMID 38774869, 2024). "In IL12Rβ1 patients, other clinical manifestations, such as autoimmunity and inflammatory bowel disease (IBD), have been described." (PMID 38535546, 2024). "The observed reduction in the Th17 cell population in the patient strongly suggests its potential involvement in the development of inflammatory bowel disease in this individual, aligning with the clinical manifestations seen in IL-12Rb1 patients, such as autoimmunity and IBD." (PMID 38535546, 2024). "The role of IL-12 and IL-23 signaling in the development of IBD is highlighted by the fact that patients with complete loss-of-function mutations in IL23R, IL12RB1, or IL12B do not develop spontaneous inflammatory bowel disease." (PMID 39795980, 2024).
salmonellosis (5 papers, 2021 to 2023). Infections with bacteria of the genus salmonella. "IL12B or IL12RB1 deficiency and salmonellosis should be considered in MSMD patients with vasculitis." (PMID 34389021, 2021). "One of the intriguing phenomena is that, although IL12RB1 deficiency increases the susceptibility to childhood-onset mycobacteriosis and salmonellosis, the recurrence of mycobacterial disease is rare, while the recurrence of salmonellosis is much more frequent." (PMID 35891311, 2022). "Of note, IL12RB1 deficiency has been reported in an A-T patient with atypical features such as extraintestinal, nontyphoidal salmonellosis." (PMID 34686943, 2022).
Autoimmunity (4 papers, 2017 to 2024). The occurrence of an immune reaction against the organism's own cells or tissues. "In contrast to other primary immunodeficiency diseases, there is only scarce evidence for association of defects of the IL-12/IFN-γ axis, including IL12Rβ1 deficiency with autoimmunity." (PMID 28804486, 2017). "This is the first association of a primary immunodeficiency with autoimmunity in the form of SS and a very rare case of manifested autoimmunity in case of IL12Rβ1-deficiency." (PMID 28804486, 2017). "IL-12Rβ1 defect also results in TH17 pathway defect that can be associated with autoimmunity and auto inflammation which could be the cause of IBD in our patients." (PMID 33732252, 2021). "Apart from evidence on the pathogenic involvement of IL-12 in SS, persistent antigenic stimulation as a consequence of recurrent or persistent infection—especially of a mycobacterial infection—in IL12Rβ1-deficiency, may contribute or lead to autoimmunity." (PMID 28804486, 2017). "LncRNAs can also regulate autoimmunity, as the expression of lncRNA-A930015D03Rik and -1055 is strongly correlated with IL12Rβ1, one of the essential molecular markers in Th1 response pathway." (PMID 30523422, 2018). "Autoimmunity in MSMD has not been reported any literature, presence of multiple autoimmunity in our cohort of IL-12Rβ1 requires further investigation and may indicate need for screening MSMD patients for autoimmune diseases." (PMID 33732252, 2021).
histoplasmosis (4 papers, 2017 to 2023). A disease caused by the fungus Histoplasma capsulatum. "Impaired IL-12p70 induction probably contributed to the disseminated histoplasmosis observed in P1, as such infections are frequently reported in patients with complete IL-12Rβ1 or IL-12p40 deficiencies." (PMID 36736301, 2023). "In contrast, disseminated histoplasmosis occurred in IL-12Rβ1 deficiency, IFN-γR1 deficiency, and GOF STAT1 defect, but 7 out of 10 cases of histoplasmosis in hyper-IgE syndrome involved the aerodigestive tract only." (PMID 28702025, 2017).
psoriasis (4 papers, 2009 to 2023). An autoimmune condition characterized by red, well-delineated plaques with silvery scales that are usually on the extensor surfaces and scalp. "Furthermore, the higher prevalence of psoriasis in the intrinsic immunity defects (IL12RB1 variant) group could be attributed to the role of IL-12 in psoriasis pathogenesis." (PMID 37237458, 2023).
viral infection (4 papers, 2019 to 2023). "IL12RB1, a subunit of the interleukin 12 receptors is associated with tyrosine kinase 2 (TYK2), which plays a pivotal role in immunity to viral infection and cancer surveillance." (PMID 37228491, 2023).
colorectal cancer (3 papers, 2021 to 2023). A primary or metastatic malignant neoplasm that affects the colon or rectum. "For this reason, we screened 7 m6A-related genes (IL12RB1, FASLG, CXCL13, GBP2, CXCL10, CXCR6, and CIITA) through WGCNA and LASSO regression in this study and established an m6A-GPI in colorectal cancer." (PMID 37427112, 2023).
leukocytoclastic vasculitis (3 papers, 2021 to 2022). "However, we report a case of IL12RB1 deficiency presenting with a maculopapular eruption, proven by a skin biopsy to be leukocytoclastic vasculitis." (PMID 35198320, 2022).
lung carcinoma (3 papers, 2018 to 2023). "It was found that elevated expression of tumor tissue IL12RB1 was associated with lung cancer progression, whereas its correlation with CRC development has not been reported." (PMID 37228491, 2023).